IRF6 (interferon regulatory factor 6)
Diseases named in the same sentence as IRF6 in open-access papers (continued):
Sharing a sentence is not in itself a finding about the gene and the disease.
squamous cell carcinoma (18 papers, 2014 to 2025). A carcinoma arising from squamous epithelial cells. "IRF6 was implicated to exhibit tumor suppressor activity in squamous cell carcinomas, and also scored as a hit in our in vivo CRISPR screen elucidating long-tail HNSCC genes." (PMID 36765696, 2023). "Previous studies also found that IRF6 exhibited tumor suppressor activity in several cancer, while promoter hypermethylation of IRF6 was associated with poor prognosis in gastric cancer and squamous cell carcinoma." (PMID 33874979, 2021). "IRF6 was implicated as a tumor suppressor in squamous cell carcinoma (SCC)." (PMID 26161746, 2015). "IRF6 also acts as a tumor suppressor in human squamous cell carcinomas, in which its expression is commonly inhibited." (PMID 40569988, 2025). "IRF6 regulated by TP63 plays a tumor suppressor role in squamous cell carcinomas through a Notch-dependent mechanism, which plays critical roles in EMT pathway." (PMID 33156825, 2020). "IRF6 was reported to be positively regulated by TP63 in squamous cell carcinomas and normal skin tissues." (PMID 31019894, 2019). "Due to IRF6 was known to be a target gene of TP63 in skin development and squamous cell carcinomas, we firstly attempted to analyze the co-expression of IRF6 and TP63 in human gastrointestinal tissues." (PMID 31019894, 2019). "While the function of IRF6 in cancers has only been reported in squamous cell carcinomas and breast cancer." (PMID 31019894, 2019). "In squamous cell carcinomas, IRF6 expression is downregulated and knockdown of IRF6 promotes invasive behavior of tumor cells." (PMID 31019894, 2019). "IRF6 is likely to promote inflammation to Porphyromonas gingivalis through its regulation of IL-36γ, and exhibits tumor suppressor activity in squamous cell carcinomas." (PMID 31156544, 2019). "IRF6 is also a potential tumor suppressor gene in squamous cell carcinomas acting on a gene network that contributes to the regulation of cancer cell invasiveness and proliferation." (PMID 25547932, 2014). "Although previous studies have indicated that IRF6 also plays important roles in multiple tumors, including gastric cancer 13, nasopharyngeal carcinoma 14, squamous cell carcinoma 15 and cervical cancer 16, the expression pattern and prognostic value of IRF6 in ccRCC are still uncertain." (PMID 34659554, 2021). "In other words, IRF6 plays a tumor suppressor role in squamous cell carcinomas and breast cancer." (PMID 31019894, 2019). "Moreover, Irf6 protein tends to be downregulated in breast, nasopharyngeal, and squamous cell carcinomas." (PMID 30545388, 2018). "The protein product of IRF6 has been shown to function synergistically with the tumor suppressor maspin to regulate mammary epithelial differentiation, and has also been shown to have tumor suppressor activity in squamous cell carcinoma." (PMID 25146004, 2014). "One example is interferon regulatory factor 6 (IRF6) which was strongly downregulated by YAP5SA and which has been shown to inhibit migration and cell invasion in squamous cell carcinomas and colorectal cancer cells." (PMID 36864753, 2023). "Recent studies have proved that IRF6, regulated by TP63, plays a tumor suppressor role in squamous cell carcinomas through a Notch-dependent mechanism." (PMID 31019894, 2019). "Besides, it's reported that IRF6 is aberrantly silenced by DNA methylation of the 5′ IRF6 CGI in melanoma and squamous cell carcinomas." (PMID 31019894, 2019). "Similar to our results, IRF6 (INF regulatory factor 6), a pro-differentiating factor which shares similar expression pattern to that of S100A16, has been shown to have a tumor suppressive activity in squamous cell carcinoma by promoting keratinocyte differentiation." (PMID 26353754, 2015).
breast carcinoma (16 papers, 2014 to 2024). "Study has shown that IRF6 can be used as the downstream of Notch signaling pathway to regulate the proliferation and transformation of breast cancer cells, and can also be used as a potential susceptibility marker of breast cancer." (PMID 33941190, 2021). "Moreover, we observed that neoadjuvant trastuzumab-based treatments of patients with locally advanced breast cancer tend to cause Irf6 upregulation in tumors." (PMID 30545388, 2018). "Furthermore, we found that the anti-ErbB2 antibody trastuzumab used for ErbB2-positive breast cancer treatment upregulates Irf6 in BT-474 cells much more noticeably than in their variant selected for trastuzumab resistance by prolonged cell exposure to trastuzumab in 3D culture." (PMID 30545388, 2018). "Thus, ErbB2 likely downregulates Irf6 levels in patients’ tumors, and Irf6 upregulation may be associated with trastuzumab sensitivity of breast cancer cells." (PMID 30545388, 2018). "The protein expression levels of TNFAIP6, IFRD1, IFNGR1, and IRF6 were analyzed in 125 breast cancer samples and 18 normal samples by using the UALCAN dataset." (PMID 39765744, 2024). "We found that ErbB2 promotes survival of breast cancer cell detached from the ECM by a novel mechanism involving downregulation of transcription factor IRF6 and further downregulation of the cell death-promoting protein BLNK." (PMID 35933456, 2022). "We found previously that ErbB2 downregulates IRF6 in breast cancer cells by activating protein kinase MEK." (PMID 35933456, 2022). "We show here that ErbB2-dependent IRF6 downregulation reduces cellular levels of the pro-apoptotic protein BLNK and that BLNK loss blocks anoikis of breast cancer cells and promotes their tumorigenicity in vivo." (PMID 35933456, 2022). "IRF6 functions as a tumor suppressor gene in breast cancer, cervical cancer and nasopharyngeal carcinoma." (PMID 35443865, 2022). "We found previously that ErbB2 blocks breast cancer cell anoikis by downregulating transcription factor IRF6." (PMID 35933456, 2022). "We found that ErbB2 downregulates IRF6 in breast cancer cells by activating a protein kinase MEK and its target protein kinase ERK." (PMID 35933456, 2022). "In summary, ErbB2-induced BLNK downregulation in detached breast cancer cells is driven by IRF6 downregulation." (PMID 35933456, 2022). "In breast cancer, IRF6 overexpression results in a significant reduction of breast cancer cell numbers through arresting cell cycles." (PMID 31019894, 2019). "Previous studies have reported that IRF6 was downregulated during EMT process of breast cancer and prostate cancer." (PMID 31019894, 2019). "We have also shown that ErbB2, a major oncoprotein, downregulates Irf6 in breast cancer cells growing in a 3D manner." (PMID 30545388, 2018). "We have further demonstrated that the effect of ErbB2 on Irf6 can be blocked by ErbB2-targeted drugs such as trastuzumab in cultured breast cancer cells and in patients’ tumors." (PMID 30545388, 2018). "Our results are relevant to breast cancer because Irf6 tends to be downregulated in this malignancy." (PMID 30545388, 2018). "We observed that lapatinib, a small-molecule ErbB2/EGFR inhibitor used for treatment of ErbB2-positive breast cancer, strongly upregulates Irf6 in detached ErbB2-positive human breast cancer cells BT-474, AU-565, and HCC-1419." (PMID 30545388, 2018). "In the breast, it was shown that IRF6 expression was reduced in breast cancer cell lines and invasive tumors." (PMID 26161746, 2015). "In breast cancer cell lines ectopic expression of IRF6 reduces cell numbers suggesting a role as negative regulator of cell cycle." (PMID 26161746, 2015). "Overall, the data suggest that IRF6 expression in breast cancer cell lines with active Notch signaling is, at least partially, dependent on canonical Notch signaling." (PMID 26161746, 2015).
breast carcinoma (continued). "The most interesting crosstalk between breast cancer cell proliferation and maspin offers two interactions of maspin: with IRF6 transcription factor and with HDAC1 in a GST-dependent manner." (PMID 24581141, 2014). "Thus, our data are consistent with a model whereby ErbB2-dependent ERK activation downregulates IRF6, IRF6 downregulation causes reduction in the cellular BLNK levels, whereas BLNK loss in turn inactivates p38MAPK and thus blocks breast cancer cell anoikis." (PMID 35933456, 2022). "Downregulation of IRF6 was demonstrated in highly invasive breast cancer cell lines and when elevated, it suppressed cell proliferation, and enhanced sensitivity to chemotherapy, but the impacts of IRF6 on cardiovascular diseases remain largely unknown." (PMID 34944912, 2021). "PI3K regulatory subunit PIK3R2 could also be modulated by IRF6 through the PI3K‐Akt pathway to control the pathogenesis of breast cancer." (PMID 33934391, 2021). "In all 11 cases, breast cancer cells displayed very low cytoplasmic Irf6 staining." (PMID 30545388, 2018). "Exploring whether Irf6 can serve as a biomarker of breast cancer trastuzumab sensitivity represents a promising direction for our future studies." (PMID 30545388, 2018). "One approach to testing whether ErbB2 downregulates Irf6 in human breast cancer is to examine whether therapies based on the use of a therapeutic anti-ErbB2 antibody trastuzumab upregulate Irf6 in patients’ tumors." (PMID 30545388, 2018). "Moreover, we performed Irf6 IHC analysis of tumor samples derived from the locally advanced ErbB2-positive breast cancers before and after neoadjuvant trastuzumab-based therapies." (PMID 30545388, 2018). "Studies have shown that IRF6 is low expressed in gastric cancer, and it has been recently reported that increased IRF6 expression can inhibit the proliferation, invasion and tumorigenicity of breast cancer cells and enhance the sensitivity of tumor cells to chemotherapy drugs." (PMID 35443865, 2022). "The rs4648090 polymorphism has also been related to decreased risk of breast cancer among women with European ancestry and to interact with other SNPs in the IFNG, IRF2, IL6, and NFKB1 genes to affect risk of colon cancer, and with IRF6 and NFKB1 genes for risk of rectal cancer." (PMID 30781516, 2019). "Thus, ErbB2 downregulates Irf6 in detached human breast cancer cells." (PMID 30545388, 2018). "The heat map tables show the correlation between immune cell infiltrations and TNFAIP6, IFRD1, IFITM2, IFNGR1, IRF6, and NFIL3 in breast cancer." (PMID 39765744, 2024). "A significant positive correlation between IRF6 and ESR1 expression was found in Basal and Luminal A subtypes, giving a good marker for breast cancer patients." (PMID 39765744, 2024). "To address the consequences of low IRF6 and GRHL3 levels in cancer cell lines, we rescued their expression in the breast cancer cell line T47D and in the oral squamous carcinoma cell line SCC-68." (PMID 36457487, 2022). "We also observed that a small molecule proteasome inhibitor bortezomib used for multiple myeloma treatment upregulates IRF6 and BLNK in detached ErbB2-positive breast cancer cells and kills them in a BLNK-dependent manner." (PMID 35933456, 2022). "We used Taqman qPCR to investigate the correlation between the differential methylation of IRF6, SLFN12, and RNF39 with their gene expression at baseline and after the first cycle of DOX chemotherapy in PBMCs of breast cancer patients." (PMID 34944912, 2021). "To test whether ErbB2 downregulates Irf6 in human ErbB2-positive breast cancer cells, we examined the effect of ErbB2 inhibitors, such as the anti-ErbB2 antibody trastuzumab or the ErbB2/epidermal growth factor receptor small-molecule inhibitor lapatinib, on Irf6 in these cells." (PMID 30545388, 2018). "In breast cancer, ER-regulated genes including FGFR1 and IRS1, and ERK1-regulating genes including IRF6 and TOM1L1, were aberrantly methylated." (PMID 24842468, 2014).
breast carcinoma (continued). "Concomitantly with this in breast cancer cell lines (MCF-7 and MDA-MD-231) overexpression of IRF6 together with maspin (located cytoplasmically) induced a synergistic effect of inhibition of proliferation but not total inhibition of proliferation." (PMID 24581141, 2014). "In search for pharmacological approaches allowing to upregulate BLNK in tumor cells we found that clinically approved proteasome inhibitor bortezomib upregulates IRF6 and BLNK in human breast cancer cells and inhibits their 3D growth in a BLNK-dependent manner." (PMID 35933456, 2022). "In the breast cancer cell line T47D, elevated IRF6 and GRHL3 did not modulate EMT marker expression." (PMID 36457487, 2022). "Indeed, we observed that a small molecule proteasome inhibitor bortezomib used for multiple myeloma treatment upregulates both IRF6 and its target BLNK in ErbB2-positive breast cancer cells BT474." (PMID 35933456, 2022). "In addition, previous studies showed that IRF6 is a downstream target gene of the NOTCH signaling pathway and induced by the NOTCH signaling pathway in breast cancer and keratinocytes." (PMID 31019894, 2019). "Of note, we found that ErbB2-targeted drugs such as trastuzumab upregulate Irf6 in trastuzumab-sensitive but not in trastuzumab-resistant ErbB2-producing detached human breast cancer cells." (PMID 30545388, 2018). "Furthermore, IRF6 was accumulated upon cell cycle arrest in MCF10A cells and its adenoviral overexpression in breast cancer cell lines reduced cell numbers, implicating IRF6 as a negative regulator of cell cycle." (PMID 26161746, 2015). "On the other hand, IFNGR1, IRF6, and NFIL3 were present in the Basal subtype as well as before tumor formation in the cell line of the model, indicating that they could be good markers for Basal subtype breast cancer patients." (PMID 39765744, 2024). "Overall survival analysis showed that TNFAIP6, IFITM2, IFNGR1, and IRF6 expression levels were not significant, whereas IFRD1 (n = 568) indicated a significantly (p < 0.05) increased risk in Luminal A breast cancer patients, along with NFIL3 (n = 219) in Luminal B patients with similar significance." (PMID 39765744, 2024). "The IRF6 expression level was significantly (p < 0.05) positive in Luminal A patients, and the correlation between NFIL3 gene expression levels and neutrophils was significantly (p < 0.05) positive in every breast cancer subtype, including Basal, Her2, Luminal A, and Luminal B." (PMID 39765744, 2024). "A significant (p < 0.05) positive correlation was also observed between ESR1 and IRF6 gene expression levels in Basal and Luminal A breast cancer patients, and there was also a significant (p < 0.05) positive correlation between ESR1 and NFIL3 gene expression levels in Basal breast cancer patients." (PMID 39765744, 2024). "Furthermore, it has been found that IRF6 (target of TP63) is induced by the NOTCH signaling pathway, which plays vital roles in the development and progression of cancers through regulating ZEB1 expression and EMT pathway, in breast cancer and keratinocytes." (PMID 33156825, 2020). "Therefore, the downregulation of IRF6 in GC or in EMT process of GC, SCC and breast cancer may be due to upregulation of ZEB1." (PMID 31019894, 2019). "Cell cycle arrest resulted in IRF6 accumulation in MCF10A cells, non-tumorigenic immortalized breast epithelial cell line, while ectopic expression with adenoviral vectors in breast cancer cell lines MCF7 and MDA MB 231 led to decreased cell numbers." (PMID 26161746, 2015). "It was found that IRF6 was accumulated due to cell cycle arrest in the non-tumorigenic immortalized breast epithelial cell line MCF-10A, but ectopic expression by adenoviral vectors resulted in reduced cell counts in breast cancer cell lines such as the MCF7 and MDA-MB-231 cell lines." (PMID 39765744, 2024).
gastric cancer (10 papers, 2019 to 2025). A primary or metastatic malignant neoplasm involving the stomach. "This aligns with emerging evidence that elf3 directly binds to the IRF6 promoter in a human gastric cancer cell line and to the interferon epsilon promoter in HEK293 cells." (PMID 41147741, 2025). "Like NPC, IRF6 expression is also commonly decreased in human gastric cancer, and IRF6 expression in gastric carcinomas is correlated with better patient survival." (PMID 40569988, 2025). "And the decreased expression of IRF6 was clinically correlated with poor prognosis of Gastric cancer." (PMID 35012444, 2022). "Considering highly similar expression profile between ELF3 and IRF6 in normal human stomach tissues, we wanted to know if ELF3 and IRF6 were still co-expressed in the gastric cancer tissues." (PMID 31019894, 2019). "The results showed that the transcripts level of IRF6 in the gastric cancer tissues was lower than in the corresponding normal tissues." (PMID 31019894, 2019). "In this study, we determined to investigate the function of transcription factor IRF6 in gastric cancer." (PMID 31019894, 2019). "Nevertheless, we found that IRF6 expression was negatively related to its promoter methylation in TCGA stomach cancer cohorts." (PMID 31019894, 2019). "Likewise, IRF6 expression has been reported to be reduced in gastric cancers via DNA methylation of the IRF6 gene promoter, and decreased IRF6 expression in gastric carcinoma correlates with poor clinical prognosis." (PMID 40569988, 2025). "A study reported that IRF6 expression is down-regulated in gastric cancer and is associated with poor prognosis, which may be caused by overexpression of ZEB1 and DNA methylation of IRF6 promoter." (PMID 33941190, 2021). "Besides, the decreased expression level of IRF6 was closely related to malignant progression and poor prognosis of gastric cancer." (PMID 31019894, 2019). "Due to the reason why IRF6 was downregulated in these 3 cancer types remains largely unclear, our following studies focused on identifying the possible transcriptional regulators of IRF6 in gastric cancer." (PMID 31019894, 2019). "It was identified that ELF3 was co-expressed with IRF6 in all five gastric cancer GSE datasets." (PMID 31019894, 2019). "Additionally, the result of CHIP assay showed that ZEB1 could directly bind on the IRF6 promoters in gastric cancer cells." (PMID 31019894, 2019). "In order to understand the significance of decreased IRF6 expression in gastric cancer, we further determined the potential associations between IRF6 expression level and clinicopathological features in GSE62254 GC cohorts (n = 300)." (PMID 31019894, 2019). "And the CHIP assay in gastric cancer cells showed that ZEB1 could bind on IRF6 promoter." (PMID 31019894, 2019). "Further, in gastric cancer, an antagonistic relation between ZEB1 and ELF3 was observed through their downstream targets, such as IRF6." (PMID 36864480, 2023). "Likewise, we find that IRF6 is also required for efficient TPA-induced lytic EBV reactivation in both an EBV + NPC cell line (NPC43) and an EBV+ gastric carcinoma cell line (SNU719)." (PMID 40569988, 2025).